TMED2 (transmembrane p24 trafficking protein 2)
Description:
Involved in vesicular protein trafficking. Mainly functions in the early secretory pathway but also in post-Golgi membranes. Thought to act as cargo receptor at the lumenal side for incorporation of secretory cargo molecules into transport vesicles and to be involved in vesicle coat formation at the cytoplasmic side. In COPII vesicle-mediated anterograde transport involved in the transport of GPI-anchored proteins and proposed to act together with TMED10 as their cargo receptor; the function specifically implies SEC24C and SEC24D of the COPII vesicle coat and lipid raft-like microdomains of the ER. Recognizes GPI anchors structural remodeled in the ER by PGAP1 and MPPE1. In COPI vesicle-mediated retrograde transport inhibits the GTPase-activating activity of ARFGAP1 towards ARF1 thus preventing immature uncoating and allowing cargo selection to take place. Involved in trafficking of G protein-coupled receptors (GPCRs). Regulates F2RL1, OPRM1 and P2RY4 exocytic trafficking from the Golgi to the plasma membrane thus contributing to receptor resensitization. Facilitates CASR maturation and stabilization in the early secretory pathway and increases CASR plasma membrane targeting. Proposed to be involved in organization of intracellular membranes such as the maintenance of the Golgi apparatus. May also play a role in the biosynthesis of secreted cargo such as eventual processing.
Synonyms: p24beta1; RNP24; P24A; p24b1; p24
Tractability: Antibody: UniProt predicts a signal peptide or a membrane-spanning region. PROTAC: ubiquitination databases record sites on it; its protein half-life has been measured.
Gene: Protein-coding gene on chromosome 12 (123,584,526 to 123,598,582, forward strand). Ensembl gene ENSG00000086598.
Subcellular location: Cytoplasmic vesicle membrane; Cytoplasmic vesicle, COPI-coated vesicle membrane; Golgi apparatus, cis-Golgi network membrane; Golgi apparatus, Golgi stack membrane; Endoplasmic reticulum membrane; Endoplasmic reticulum-Golgi intermediate compartment membrane
Subcellular location (Human Protein Atlas): Vesicles
Pathways (Reactome):
Vesicle-mediated transport: COPI-dependent Golgi-to-ER retrograde traffic; COPI-mediated anterograde transport; COPII-mediated vesicle transport; Cargo concentration in the ER
Signal Transduction: Pre-NOTCH Processing in Golgi
Gene Ontology:
Molecular function: protein binding; frizzled binding; smoothened binding
Biological process: Golgi organization; intracellular protein transport; negative regulation of GTPase activity; protein localization to plasma membrane; regulation of cargo loading into COPII-coated vesicle; COPI coating of Golgi vesicle; COPII vesicle coating; endoplasmic reticulum to Golgi vesicle-mediated transport; vesicle cargo loading; embryonic morphogenesis; labyrinthine layer blood vessel development; maternal placenta development
Cellular component: endoplasmic reticulum; endoplasmic reticulum membrane; endoplasmic reticulum-Golgi intermediate compartment; endoplasmic reticulum-Golgi intermediate compartment membrane; Golgi apparatus; COPI-coated vesicle; ER to Golgi transport vesicle membrane; Golgi membrane; membrane; transport vesicle; zymogen granule membrane; COPI-coated vesicle membrane; cytoplasmic vesicle membrane; Golgi cisterna membrane
Genetic constraint (gnomAD): Loss-of-function variants: 3 observed, 17.34 expected, observed/expected ratio (o/e) 0.17, 90% interval 0.078 to 0.45. The upper end of that interval is the gene's LOEUF score, 0.45, which puts it in group 1 of 6, group 1 being the genes least tolerant of losing a copy. Missense variants: 149 observed, 258.62 expected, observed/expected ratio (o/e) 0.58, 90% interval 0.5 to 0.66. Synonymous variants: 95 observed, 93.92 expected, observed/expected ratio (o/e) 1.01, 90% interval 0.86 to 1.2.
Homologues: Orthologues: chimpanzee TMED2 (100% identical), macaque TMED2 (100% identical), rat Tmed2 (99% identical), guinea pig TMED2 (99% identical), mouse Tmed2 (99% identical), pig TMED2 (99% identical), dog TMED2 (99% identical), tropical clawed frog tmed2 (95% identical), zebrafish tmed2 (91% identical), Drosophila melanogaster p24-1 (24% identical), Caenorhabditis elegans tmed-12 (16% identical). Paralogues in human: TMED7 (35% identical), TMED3 (30% identical), TMED5 (27% identical), TMED9 (26% identical), TMED4 (25% identical), TMED1 (24% identical), TMED10 (22% identical), TMED6 (21% identical).
Diseases named in the same sentence as TMED2 in open-access papers:
TMED2 is named in the same sentence as 37 diseases in open-access papers, as found by Europe PMC text mining. Sharing a sentence is not in itself a finding about the gene and the disease. The quoted sentences say what the papers report.
ovarian carcinoma (6 papers, 2017 to 2023). A malignant neoplasm originating from the surface ovarian epithelium. "One study discovered that ovarian cancer patients had higher TMED2 levels, and that ovarian cancer cells that overexpressed TMED2 had greater cell migration and proliferation." (PMID 37928880, 2023). "It was reported earlier that increased proliferation and invasion of ovarian cancer cells were positively correlated with ectopic expression of TMED2." (PMID 35754792, 2022). "TMED2 was identified as a promoter of cell proliferation and migration in ovarian cancer cells through activating Akt and as a poor prognostic factor in patients with breast cancer." (PMID 33888099, 2021). "In contrast, elevated levels of TMED2 were found in ovarian carcinoma patients, and ectopic expression of TMED2 in ovarian cancer cells resulted in increased cell proliferation and cell migration, characteristic of metastatic cells." (PMID 31878985, 2019). "We found that expression of TMED2 was higher in epithelial ovarian cancer tissues than normal ovarian tissues." (PMID 29212217, 2017). "The regulation of TMED2 in the growth of ovarian cancer SKOV3 cells in vivo was determined using tumor xenografts model." (PMID 29212217, 2017). "We next analyzed the expression and location of TMED2 in ovarian carcinoma tissues derived from Human Protein Atlas." (PMID 29212217, 2017). "We firstly analyzed the mRNA expression of TMED2 in ovarian carcinoma derived from Oncomine database." (PMID 29212217, 2017). "Our study found that TMED2 regulates epithelial ovarian cancer progression by activating IGF2/IGF1R/PI3K/AKT pathway." (PMID 29212217, 2017). "To explore the functions of TMED2 in epithelial ovarian cancer, we predicted the candidate ceRNAs of TMED2 by bioinformatics analyses." (PMID 29212217, 2017). "The high expression of TMED2 in epithelial ovarian cancer was related to the histological grades and cancer stage." (PMID 29212217, 2017). "Our data also found that TMED2 promoted the ability of proliferation, migration, invasion in ovarian cancer cells." (PMID 29212217, 2017). "Based on these findings, TMED2 can serve as a new ovarian cancer biomarkers and a potential cancer treatment target." (PMID 29212217, 2017). "So the over-expression of TMED2 maybe promote malignant behavior of ovarian cancer by activating AKT pathway." (PMID 29212217, 2017). "Hence, we presumed that TMED2 regulation of epithelial ovarian cancer proliferation, migration and invasion involves IGF1R/IGF2/PI3K/AKT pathway." (PMID 29212217, 2017). "So we guess that inhibited this pathway maybe a potential therapy target in ovarian cancer which elevated expression of TMED2." (PMID 29212217, 2017). "We firstly investigated the mRNA level of TMED2 in six ovarian cancer cell lines using qPCR." (PMID 29212217, 2017). "Thus, TMED2 is oncogenic and a potential target for epithelial ovarian cancer therapy." (PMID 29212217, 2017).
breast carcinoma (5 papers, 2021 to 2023). "Moreover, increased TMED2 mRNA expression was substantially linked to worse overall survival (OS) in all breast cancers as well as in patients with the luminal A, luminal B, or ER-positive subtypes of the disease." (PMID 37928880, 2023). "When compared to samples from healthy breasts, TMED2 was markedly elevated in breast cancer patients." (PMID 37928880, 2023). "TMED2 was recently reported to be involved in a variety of tumors, such as multiple myeloma, breast cancer, hepatocellular carcinoma, and choriocarcinoma." (PMID 35135563, 2022). "TMED2 was recently reported to be involved in multiple myeloma, breast cancer, hepatocellular carcinoma, and choriocarcinoma." (PMID 35135563, 2022). "Up‐regulated TMED2 is an unfavourable prognostic factor in breast cancer." (PMID 33210454, 2022). "In contrast, elevated levels of TMED2 were observed in patients with ovarian and breast cancers." (PMID 33888099, 2021). "For instance, TMED2 was expressed higher in sphere-shaped clones (SCs) and might play a role in cancer cell proliferation; the increased expression of TMED2 was significantly related to unfavorable outcomes in patients with breast cancer." (PMID 35754792, 2022). "Interestingly, elevated TMED2 and TMED9 expression levels in breast cancer patients were identified as poor prognostic factors." (PMID 35754792, 2022).
lung adenocarcinoma (3 papers, 2022 to 2023). A carcinoma that arises from the lung and is characterized by the presence of malignant glandular epithelial cells. "TMED2, MOESIN, DPYSL2, and LncRNA MEG3 have been discovered to enhance the occurrence and development of patients with lung adenocarcinoma via several immune-related regulatory mechanisms." (PMID 35354488, 2022).
Non-alcoholic fatty liver disease (3 papers, 2017 to 2022). "Heterozygous mutation in TMED2 has been shown in non‐alcoholic fatty liver disease in mice." (PMID 33210454, 2022).
viral infection (3 papers, 2018 to 2022). "We have not found any particular relation between them; however, some of them might play a role in processes such as protein synthesis regulation in cardiomyocytes (PABPC1), cardiac differentiation and development (FURIN; ADAR), or cellular response to viral infection (TMED2)." (PMID 33917391, 2021). "Using a cutoff of greater than 30% increase in viral infection normalized to cell viability in two independent screens, we identified HSPA5, TMED2, SPCS2, and DDIT3 as factors whose overexpression increased DENV infection, indicating rate limitation associated with these important proviral factors." (PMID 29451494, 2018). "Interestingly, TMED2 could bind to MITA, stabilize dimerization of MITA, and promote MITA translocation from the ribosome to the ER and the Golgi after viral infection." (PMID 35754792, 2022).
colorectal cancer (2 papers, 2024 to 2025). A primary or metastatic malignant neoplasm that affects the colon or rectum. "This highlights the complex, context-dependent roles of TMED2, with tumor-promoting effects in OSCC and tumor-suppressive effects in colorectal cancer." (PMID 39879476, 2025). "Additionally, a positive correlation was identified between TMED1 and other members of the TMED family (TMED2, TMED4, TMED9, and TMED10) in colorectal cancer." (PMID 38392302, 2024).
diabetes (2 papers, 2020 to 2023). "More broadly, TMED2 and TMED10 are also linked to disorders and diseases including Alzheimer’s disease (AD), kidney disorders, and diabetes." (PMID 32293333, 2020).
glioma (2 papers, 2025). A benign or malignant brain and spinal cord tumor that arises from glial cells (astrocytes, oligodendrocytes, ependymal cells). "CCK-8 assays demonstrated that TMED2 knockdown significantly suppressed glioma cell proliferation, a finding corroborated by reduced colony size in the plate colony formation assay." (PMID 40519935, 2025). "Single-cell sequencing reveals that TMED2 is predominantly expressed in tumor cells of cervical cancer, glioma, and mesothelioma." (PMID 40519935, 2025). "Given the oncogenic effect of TMED2 in glioma, we studied the potential effect of BRD4780 on TMED2 stability." (PMID 40497947, 2025). "Single-cell sequencing further confirmed the high expression of TMED2 in tumor cells from cervical cancer, glioma, and mesothelioma." (PMID 40519935, 2025). "Our study deeply investigated TMED2’s function in tumor immunology from a pan-cancer standpoint and verified that glioma cell proliferation and invasion are inhibited by TMED2 expression suppression." (PMID 40519935, 2025). "Next, we examined TMED2 expression in tumor, immune, and stromal cells from a variety of solid tumors types, including cervical cancer, glioma, and mesothelioma." (PMID 40519935, 2025). "Importantly, TMED2 was demonstrated to promote glioma tumorigenesis by mediating EGFR recycling transport." (PMID 40497947, 2025). "Finally, experimental validation was conducted to evaluate the impact of TMED2 knockdown on abnormal biological behaviors, such as proliferation, in glioma cells." (PMID 40519935, 2025). "We used U87 and U251 glioma cells with strong TMED2 expression in our in vitro experiments to confirm this hypothesis." (PMID 40519935, 2025). "TMED2 knockdown greatly decreased the number of tumor cells migrating to the lower chamber, indicating that TMED2 enhances the migration and invasion capabilities of glioma cells." (PMID 40519935, 2025). "Furthermore, our previous studies reported that TMED2 enhances EGFR-AKT signaling in glioma by participating in EGFR recycling." (PMID 40519935, 2025). "Furthermore, cellular studies indicated that TMED2 expression promotes the growth, migration and invasion of glioma cells." (PMID 40519935, 2025). "An in-depth study investigating this relationship demonstrated a novel role for TMED2 in EGFR signaling, a process which has been shown to be crucial for promoting glioma development." (PMID 40497947, 2025). "In addition to TMED2, a recent bioinformatics study demonstrated a positive correlation between the expression of TMED4 and TMED9 and glioma aggressiveness and a negative association with patient prognosis." (PMID 40497947, 2025).
adenosquamous carcinoma (1 paper, 2025). A carcinoma composed of malignant glandular cells and malignant squamous cells. "Among histological classifications, TMED2 expression was highest in the adenosquamous carcinoma of CESC and the epithelioid subtype of UVM." (PMID 40519935, 2025).
asthma (1 paper, 2022). "In the KEGG analysis, TMED2 was negatively correlated with olfactory transduction, porphyrin, and chlorophyll metabolism and was positively correlated with allograft rejection, asthma, and the intestinal immune network for IgA production." (PMID 35135563, 2022).
cardiomyopathy (1 paper, 2022). A disease of the heart muscle or myocardium proper. "Transmembrane p24 trafficking protein 2 (TMED2) is a protein-coding gene associated with cardiomyopathy that is involved in vesicular protein trafficking." (PMID 35135563, 2022).
Crohn disease (1 paper, 2019). A gastrointestinal disorder characterized by chronic inflammation involving all layers of the intestinal wall, noncaseating granulomas affecting the intestinal wall and regional lymph nodes, and transmural fibrosis. "Thus, low levels of TMED2 are associated with quiescent Crohn's disease as a consequence of fewer AGR2 dimers, causing some inflammation." (PMID 31878985, 2019). "However, when TMED2 levels are high in the cell, homeostasis is entirely disrupted, resulting in severe acute inflammation (active Crohn's disease)." (PMID 31878985, 2019). "Interestingly, TMED2 was recently reported to play a role in Crohn's disease through the regulation of the dimeric state of AGR2 (anterior gradient 2)." (PMID 31878985, 2019).
Flavivirus Infections (1 paper, 2018). Infections with viruses of the genus FLAVIVIRUS, family FLAVIVIRIDAE. "Further in-depth studies are warranted to elucidate the role of the host factors TMED2 and ID2 in flavivirus infection." (PMID 29451494, 2018).
head and neck squamous cell carcinoma (1 paper, 2025). A squamous cell carcinoma that arises from any of the following anatomic sites: lip and oral cavity, nasal cavity, paranasal sinuses, pharynx, larynx, and salivary glands. "However, while our study focuses on OSCC, the molecular mechanisms governing TMED2 function in different cancer types, such as head and neck squamous cell carcinoma, may vary due to distinct microenvironments and signaling pathways." (PMID 39879476, 2025).
intrahepatic cholangiocarcinoma (1 paper, 2025). A carcinoma that arises from the intrahepatic bile duct epithelium in any site of the intrahepatic biliary tree. "VIRMA can maintain the stability of TMED2 and PARD3B through m6A HuR mediation, activate the Akt/GSK/β- catenin and MEK/ERK/Slug signaling pathways, thereby promoting further deterioration of intrahepatic cholangiocarcinoma (ICC)." (PMID 41256854, 2025).
lung carcinoma (1 paper, 2022). "TMED2 expression in LUAD tumor tissues was higher than that in normal tissues and positively correlated with poor survival in lung cancer and negatively correlated with apoptosis in LUAD." (PMID 35135563, 2022).
lung diseases (1 paper, 2022). "For the majority of genes such as Elac2, Csnk1a1, Eif3a, Eif4g2, Tmed2 and Mpv17l, a role in the pathogenesis of lung diseases was indicated by previous studies, although their functions in the neonatal lung remain unexplored." (PMID 36271035, 2022).
oral squamous cell carcinoma (1 paper, 2025). "This study aimed to investigate the role of transmembrane emp24 domain-containing protein 2 (TMED2) in oral squamous cell carcinoma (OSCC)." (PMID 39879476, 2025).
ovarian clear cell adenocarcinoma (1 paper, 2017). A malignant glandular epithelial neoplasm characterized by the presence of clear and hobnail cells. "However, the expression difference of TMED2 between ovarian clear cell adenocarcinoma and normal ovarian tissues is not significant(P=0.102)." (PMID 29212217, 2017).
rectal tumor (1 paper, 2022). "The results showed that TMED2 expression was increased in rectal tumor tissue and in HCC827 cells, which were consistent with the results of the bioinformatics analyses." (PMID 35135563, 2022).